SNAI1 (snail family transcriptional repressor 1)
Diseases named in the same sentence as SNAI1 in open-access papers (continued):
Sharing a sentence is not in itself a finding about the gene and the disease.
breast cancer (continued). "Totally, we explored a potential mechanism that FBXL10/SNAI1/HDAC1 axis promoted EMT and metastasis of breast cancer cells." (PMID 34718323, 2021). "Overexpression of SNAI1, TWIST1, and ZEB1 in breast cancer is sufficient to increase the CD44+/CD24lo stem cell pool, resulting in increased sphere forming capacity in vitro, as well as elevated tumorigenicity and metastasis in vivo." (PMID 34459003, 2021). "BRD4 inhibition suppresses the expression of Gli1, which is required for transcriptional activation of SNAI1, indicating that BRD4 controls malignancy of breast cancer cells via both transcriptional and post-translational regulation of SNAI1." (PMID 34681726, 2021). "Activated HIF1α or HIF2α directly or indirectly regulate SNAI1, TWIST1 and ZEB1 expression which fosters stemness and metastasis formation in bladder, ovarian, gastric and breast cancer." (PMID 34459003, 2021). "Mutual exclusivity data from the n = 1,105 breast cancer TCGA dataset revealed that PAPP-A has a significant tendency towards co-occurrence with mesenchymal markers Vimentin (VIM), SNAI1 (Snail), SNAI2 (Slug), Zeb1, Zeb2 and Twist1." (PMID 32792532, 2020). "Remarkably, CD24 is a direct target of Wnt1 in breast cancer, while CD47 is an indirect target of Wnt signaling mediated by SNAI1 and ZEB1 in breast cancer." (PMID 33234169, 2020). "In this study, we observe that Snail (SNAI1), a key transcriptional repressor of epithelial–mesenchymal transition, enhances catabolic FAO, allowing pro-survival of breast cancer cells in a starved environment." (PMID 32487689, 2020). "They functionally observed that Snai1 activation induced by DDR2 increased in vitro migration and invasion and in vivo metastatization of breast cancer cell lines." (PMID 32793478, 2020). "Similarly, KDM6B has also been associated with the direct activation of the EMT-TF gene SNAI1, or SNAI2, in different cancer models (breast cancer cells, hepatocarcinoma cells, and CRCCs) but KDM6B might also be recruited on specific promoters involved in downstream EMT signaling." (PMID 33291363, 2020). "Importantly, both Snail Family Transcriptional Repressor 1 (SNAI1) and Eukaryotic Translation Initiation Factor 5A (EIF5A) have been associated with the induction of the epithelial-to-mesenchymal transition (EMT) in breast cancer, promotion of breast cancer metastasis, and chemoresistance." (PMID 32873298, 2020). "We thus examined the relationship between the mRNA expression levels of TGFB1 (TGFβ), CTNNB1 (β-catenin), SNAI1, SNAI2 and ZEB1 and those of Sipa1 in TCGA breast cancer patient samples." (PMID 32193333, 2020). "We have determined that besides its well-defined function in the p38-inflammatory pathway, MKK3 can induce MYC-dependent epithelial-to-mesenchymal transition in breast cancer patients in part through upregulation of EIF5A, EIF5AL1, and SNAI1 genes." (PMID 32873298, 2020). "In invasive breast cancer cell lines, depletion of KDM6A leads to an increase in Myc-dependent EMT factors including SNAI1 and ZEB1/2." (PMID 33003334, 2020). "Studies have revealed that DACH1 inhibits SNAI1, and TGF‐β‐mediated EMT is involved in breast cancer, which promoted us to explore the possibility that DACH1 regulates EMT in progestin resistance." (PMID 31215145, 2019). "Earlier studies reported that SNAI1 and SNAI2 displayed a reciprocal expression in oral, breast cancer cells or during reprogramming of induced pluripotent stem cells." (PMID 31165775, 2019). "Studies had shown that degrading PTEN through lysosome-mediated activation of PI3K/AKT/GSK3β/SNAI1 signaling pathway could promote the metastasis and progression of EMT and breast cancer tumors, which showed that the loss of PTEN contributed to the development of breast cancer." (PMID 30713576, 2019). "Recent data have suggested that SNAI1 and SNAI2 are differentially expressed in normal mammary glands and in mammary tumours that distinctly induces EMT program." (PMID 31165775, 2019).
breast cancer (continued). "Recently, we reported the expression of NRP-1 and other associated molecules in the plasma, immune cells, and tumor tissue of a breast cancer patients' cohort and confirmed the role of NRP-1, PlGF, and SNAI1 in breast cancer progression." (PMID 31106153, 2019). "Among individual transcripts identified by this analysis were several genes known to be associated with the metastatic process (ALCAM, MALAT1) and EMT (SNAI1, GSC, FOXC2, SIP1) and breast cancer stem cells (CD44)." (PMID 29291741, 2018). "In breast cancer cells, VEGF-A increases mRNA and protein level for SNAI1, resulting in repression of E-cadherin transcription." (PMID 29337896, 2018). "Breast cancer patients displayed significantly decreased expression of NRP-1 (p < 0.0001), SNAI1 (p < 0.0001) and SEMA4A (p < 0.0001) in PBMCS compared to healthy controls." (PMID 28607365, 2017). "In previous studies, we found that SNAI1 cooperates with ERα and DACH1 to regulate E-cadherin expression and EMT in breast cancer cells by binding with the E-box of the E-cadherin promoter." (PMID 29163781, 2017). "Phenformin also dose-dependently upregulated mRNA levels of CDH1 with concomitant downregulation of VIM, SNAI1, and SNAI2, indicating that phenformin hinders EMT at the transcriptional level in breast cancer cells." (PMID 28947975, 2017). "hsa-miR-661 is known to be expressed at early time points of SNAI1-induced EMT and promote invasion of breast cancer cells by degrading two target genes, NECTIN1 (cell-cell adhesion protein), and STARD10 (lipid transferase)." (PMID 28793339, 2017). "The molecular mechanism governing the ability of SNAI1 and SEMA4A in PBMCs to safeguard the initiation or progression of breast cancer needs to be studied in further detail to determine methods to tap this defensive mechanism in treating cancer patients." (PMID 28607365, 2017). "On the contrary, the decreased expression of NRP-1 in addition to SNAI1 and SEMA4A in PBMCs in the cancer cohort studied compared to healthy controls highlights their potential protective role against breast cancer." (PMID 28607365, 2017). "Secondly, this study implies the protective role of NRP-1, SNAI1 and SEMA4A expression in PBMCs in healthy controls and early stage breast cancer patients." (PMID 28607365, 2017). "AXL was shown to control the expression of the transcription factors SNAI1/2 and TWIST1/2 in pancreatic cancer and, in breast cancer, to activate the AKT/GSK3β/β-Catenin cascade that induces expression of ZEB1 and other EMT-related genes." (PMID 28251492, 2017). "CDH2 (encoding N-cadherin), VIM (encoding vimentin), TWIST1/2 (products which are EMT transcriptional factors) and SNAI1, as well as ZEB1, are well known key players involved in EMT-like processes of breast cancers." (PMID 27617643, 2016). "The products of SNAI1 (Snail) and SNAI2 (Slug) genes are master regulators of EMT and their elevated levels confer poor prognosis in breast cancer." (PMID 25820424, 2015). "Analysis of tissue samples taken from human breast cancers showed a significant correlation between the expression of DACH1 and E-cadherin in SNAI1-positive breast cancer." (PMID 25775416, 2015). "We therefore analyzed the expression of mesenchymal markers connected with EMT activation (VIM, TWIST1, SNAI1 and SNAI2) in PT, CTCs-EBF and LNM of breast cancer patients." (PMID 24217115, 2013). "For example, SNAI1 transcribes CXCL1 and CXCL2 to regulate MDSCs infiltration in breast cancer." (PMID 41280721, 2025). "SNAI1 enhancer RNA depletion inhibits the EMT process and chemoresistance of breast cancer cells." (PMID 41211430, 2025). "A study conducted on human breast cancer found that when SNAI2 (SLUG) and SNAI1 (SNAIL) are transfected into MCF10A cells, human breast cancer epithelial cells lose their epithelial-type shape and acquire mesenchymal-related characteristics, and this was linked to AXL increase." (PMID 38391974, 2024).
breast cancer (continued). "Kaempferol induces the cell cycle at the G2/M phase in MDA-MB-453 breast cancer cells and reverses the EMT process in gastric, ovarian, and breast cancer cells by modulating key markers such as E-cadherin, Smad2/4, TGF-β, N-cadherin, vimentin, and Snai1." (PMID 39275063, 2024). "Furthermore, a feed‐forward loop initiated by SDHC knock‐out in breast cancer cells mediated enhanced TWIST1 and SNAI1 expression favoring SDHC suppression and reduction of SDH complex activity." (PMID 37899663, 2024). "Similarly, during breast cancer, TGF-β activates SMAD3, which recruits SETDB1 to methylate H3K9, while repressing H3K9 acetylation to inhibit the transcription of Snai1 (snail family transcriptional repressor 1) gene." (PMID 38057834, 2023). "Strikingly, SNAI1 protein expression levels correlated with lymph node invasion while a negative correlation of active PKD1 and FBXO11 with SNAI1 was observed in clinical breast cancer samples." (PMID 37293129, 2023). "In line with this, Lu and collegues concluded that inhibition of bromodomain-containing protein 4 (BRD4) in TNBC cell lines regulates SNAI1 in a PKD1-dependent manner, resulting in decreased migration and invasion in breast cancer cells and reduced tumor growth and metastasis in xenograft models." (PMID 37293129, 2023). "Also, SMAD3-mediated recruitment of SETDB1 to the SNAI1 promoter region to decrease Snail1 expression and EMT has been described in breast cancer." (PMID 37369946, 2023). "Furthermore, hMSCs from both sources also increased the expression levels of MYC, SNAI1, and TWIST, which promote the epithelial-mesenchymal transition and migration of breast cancer cells in both cell lines." (PMID 36406002, 2022). "Taken together, these results revealed that FBXL10 physically interacted with SNAI1 in breast cancer cells, but not SLUG or ZEB1." (PMID 34718323, 2021). "The IL-8/CXCR2/WNT feedback loop was also observed in the development of chemoresistance and metastasis in estrogen receptor (ER)-positive breast cancer, in which WNT signaling is specifically mediated by WNT3A coupled with SNAI1/nuclear factor (NF)-κB signaling activation." (PMID 34799554, 2021). "Notably, our data also indicate that an increase in RNF8 and SNAI1 mRNA levels and a decrease in CDH1 mRNA were observed in malignant subtypes of breast cancer, i.e., TNBC patients." (PMID 34357122, 2021). "In breast cancers, DOT1L forms a transcriptionally active complex with c-Myc and p300 to facilitate H3K79 methylation and acetylation in the promoter regions of SNAI1 that enhances SNAI1 de-repression, consequently promoting EMT." (PMID 34681726, 2021). "The importance of GRP78’s interaction with LOXL2 (lysyl oxidase-like 2) was established for EMT induction in breast cancer cells; this interaction results in stimulation of the IRE1/XBP1 signaling pathway followed by expression of SNAI1, SNAI2, ZEB2, and TCF3 being the EMT drivers." (PMID 32268506, 2020). "SNAI1 expression in immune cells are downregulated in breast cancer patients and increased, similar to healthy control levels in complete responders to NAC, indicating their potential protective role in breast cancer." (PMID 31106153, 2019). "This locus contains 24 protein-coding genes, among which at least 10 (e.g. NCOA3, SNAI1/Snail1, CEBPB and PTPN1) are involved in mammary gland development, ERα-related regulation, or breast cancer, suggesting an importance of this locus for mammary gland morphogenesis." (PMID 31642473, 2019). "In fact, breast cancer cell metastasis to lung tissue in mice was not affected by decreasing EMT—by targeting EMT—triggering transcription factors such as SNAI1 (Snail) and SNAI2 (Slug) by overexpressing miR-200." (PMID 31847480, 2019). "Similarly, SNAI1 also represses phosphofructokinase platelet (PFKP) and several subunits of cytochrome C oxidase (COX) in breast cancer cells, further reinforcing a strongly glycolytic metabolic phenotype." (PMID 31277295, 2019).
breast cancer (continued). "Moreover, elevated PPIL2 inhibited EMT and breast cancer invasion by interacting with the classical EMT transcription factor, SNAI1, to enhance its ubiquitin-dependent degradation." (PMID 29352246, 2018). "Collectively, our data identified a tumor inducer, SYNJ2BP, which could activate the PI3K/AKT/GSK3β/SNAI1 signaling pathway through the lysosome-mediated degradation of PTEN, and promote both EMT and tumor metastasis during the progression of breast cancer." (PMID 29163781, 2017). "Similar to NUMB, the EMT negative regulators GATA3 and FOXA1 had significantly lower expression in the BLBC subtypes and in ER-negative and higher histological grade breast cancer patients, whereas the EMT inducers FOXC1, FOXC2 and SNAI1 mimicked the expression profile of Notch1." (PMID 27506933, 2016). "Similar to NUMB, the EMT negative regulators GATA3 and FOXA1 had significantly lower expression in the BLBC subtypes, ER-negative and higher histological grade breast cancer patients, while the EMT inducers FOXC1, FOXC2 and SNAI1 mimicked the expression profiles of Notch1." (PMID 27506933, 2016). "We compared the expression of EMT-transcriptional factors between relapse (n = 8) and non-relapse (n = 8) groups who had taxane-resistant basal breast cancer and discovered that only expression levels of SNAI1 were significantly different." (PMID 26462028, 2015). "miR-203 was shown to repress endogenous SNAI1/2, forming a double negative miR203/Snail feedback loop in breast cancer." (PMID 25004126, 2014). "To test this hypothesis, we initially established an EMT model using an epithelial breast cancer cell line, MCF-7, and examined the effect of ELE on the TGF-β1-dependent signalling pathway and the nuclear transcription factors SNAI1, SNAI2, TWIST and SIP1." (PMID 23516540, 2013). "The lack of upregulation of SNAI1 is unexpected, especially given the recently identified role of this gene in breast cancer recurrence." (PMID 16495925, 2006). "Finally, we tested whether CXCL8 and CXCL1 expressions correlate with EMT-associated genes, including VIM (gene for Vim), SNAI1 (gene for Snail1), and TWIST1 (gene for Twist1) in breast cancer cell lines using the HMS LINCS dataset." (PMID 40833805, 2025). "In breast cancer, KIAA1429 promotes the epithelial–mesenchymal transition (EMT) by increasing SMC1A (structural maintenance of chromosomes 1A) expression in an m6A modification-dependent manner, and indirectly promoting SNAIL (Snail family transcriptional repressor 1) expression." (PMID 39456252, 2024). "Additionally, the discovery of TFAP2A as a transcription activator of SNAI1 enhances our understanding of the complex molecular pathways involved in TNBC progression, emphasizing TFAP2A as a key regulator in this aggressive subtype of breast cancer." (PMID 38890750, 2024). "Furthermore, as opposed to ZEB1, SNAI1 is equally expressed in basal-like breast cancers with partial-EMT and post-EMT features." (PMID 38111531, 2023). "In breast cancer cells, reduced expression of the circadian gene PER2 was found to correlate with increased expression of the pro-EMT genes Snail Family Transcriptional Repressor 2 (SLUG), Snail Family Transcriptional Repressor 1 (SNAI1), and Twist-related protein 1 (TWIST1)." (PMID 38173841, 2023). "Interestingly ZEB1, WISP2, and SNAI1 but not SLUG strongly upregulate PD-L1 expression in breast cancer cells." (PMID 33506060, 2021). "Having demonstrated the involvement of SNAI1, further studies must be carried out to dissect whether other EMT-TFs, such as SNAI2, ZEB1, or TWIST, are also involved in the regulation of the CMTM members in breast cancer cells." (PMID 33803139, 2021). "Notably, STK39 protein levels did not correlate with the SNAI1 protein expression in breast cancer cell lines and breast cancer tissues (data not shown) because the activity of STK39 need to be activated." (PMID 34335956, 2021).
breast cancer (continued). "Finally, they demonstrated that breast cancer cell lines with an invasive phenotype frequently and overexpressing DDR2 associated with nuclear-activated Snai1 and absence of E-cadherin." (PMID 32793478, 2020). "Notably, the mRNA levels of the mesenchymal markers SLUG, SNAI1, VIM, and NCAD were increased by ectopic GREM1 expression or exogenous rhGrem1 treatment, suggesting that Grem1 induces a slightly more mesenchymal phenotype in these breast cancer cells." (PMID 31533776, 2019). "Similarly, we expanded the breast cancer input layer with the hyaluronan-mediated motility receptor (HMMR) connected to FN1; the TGFBR connected to SNAI1 and SNAI2; the interLeukin 1 receptor type I (IL1R1) and the thyroid hormone receptor beta (THRB) connected to TRAF1 and MYC, respectively." (PMID 28775339, 2017). "However, miR-203 was shown to be repressed by the transcriptional repressor SNAI1/2, forming a double-negative miR-203/SNAI1/2 feedback loop in breast cancer." (PMID 27028864, 2016). "Moreover, miR-203 was shown to repress endogenous SNAI1/2, forming a double negative miR203/Snail feedback loop in breast cancer." (PMID 25004126, 2014). "Besides, collagen type I could augment SNAI1- and LEF-1-mediated EMT in breast cancer." (PMID 36712590, 2023). "The ability of the microtubule destabilizers and, in some cell lines, ixabepilone, but not paclitaxel, to inhibit TGF-β-induced SNAI1 and Snail expression could be important for their clinical efficacy, especially in breast cancer patients whose tumours have undergone EMT." (PMID 31481735, 2019). "First, this study only preliminarily confirmed that TRIM50 was adversely correlated with the nuclear expression of the transcription factor SNAI1 and has not fully elucidated the regulatory mechanism of TRIM50 on SNAI1 in breast cancer." (PMID 39538371, 2024). "To investigate the contribution of RNF8 to cancer progression in different breast cancer subtypes, we determined RNF8, SNAI1, and CDH1 expression levels in TNBC and non-TNBC breast cancer subtypes using the TCGA RNA-seq dataset." (PMID 34357122, 2021). "Similarly, in an SNAI1-induced EMT model, EMT markedly upregulated representative YAP target genes, including AXL, CTGF, CYR61, and GLI2, in human breast carcinoma cells in media with or without serum." (PMID 40940864, 2025). "In addition to PlGF, the overexpression of SNAI1 in PBMCs, post-NAC in complete responders (no residual tumor and no nodal disease), points to its protective role in breast cancer prognosis." (PMID 31106153, 2019). "However, it has also been reported that phosphorylation of SNAI1 is not a prerequisite for its degradation, so the described mechanism may be unique to PKD1-positive breast cancer." (PMID 37293129, 2023).